TRIM21 (tripartite motif containing 21)
Description:
E3 ubiquitin-protein ligase whose activity is dependent on E2 enzymes, UBE2D1, UBE2D2, UBE2E1 and UBE2E2. Forms a ubiquitin ligase complex in cooperation with the E2 UBE2D2 that is used not only for the ubiquitination of USP4 and IKBKB but also for its self-ubiquitination. Component of cullin-RING-based SCF (SKP1-CUL1-F-box protein) E3 ubiquitin-protein ligase complexes such as SCF(SKP2)-like complexes. A TRIM21-containing SCF(SKP2)-like complex is shown to mediate ubiquitination of CDKN1B ('Thr-187' phosphorylated-form), thereby promoting its degradation by the proteasome. Monoubiquitinates IKBKB that will negatively regulates Tax-induced NF-kappa-B signaling. Negatively regulates IFN-beta production post-pathogen recognition by catalyzing polyubiquitin-mediated degradation of IRF3. Mediates the ubiquitin-mediated proteasomal degradation of IgG1 heavy chain, which is linked to the VCP-mediated ER-associated degradation (ERAD) pathway. Promotes IRF8 ubiquitination, which enhanced the ability of IRF8 to stimulate cytokine genes transcription in macrophages (By similarity). Plays a role in the regulation of the cell cycle progression. Enhances the decapping activity of DCP2. Exists as a ribonucleoprotein particle present in all mammalian cells studied and composed of a single polypeptide and one of four small RNA molecules. At least two isoforms are present in nucleated and red blood cells, and tissue specific differences in RO/SSA proteins have been identified. The common feature of these proteins is their ability to bind HY RNAs.2. Involved in the regulation of innate immunity and the inflammatory response in response to IFNG/IFN-gamma. Organizes autophagic machinery by serving as a platform for the assembly of ULK1, Beclin 1/BECN1 and ATG8 family members and recognizes specific autophagy targets, thus coordinating target recognition with assembly of the autophagic apparatus and initiation of autophagy. Also regulates autophagy through FIP200/RB1CC1 ubiquitination and subsequent decreased protein stability. Represses the innate antiviral response by facilitating the formation of the NMI-IFI35 complex through 'Lys-63'-linked ubiquitination of NMI. During viral infection, promotes cell pyroptosis by mediating 'Lys-6'-linked ubiquitination of ISG12a/IFI27, facilitating its translocation into the mitochondria and subsequent CASP3 activation. When up-regulated through the IFN/JAK/STAT signaling pathway, promotes 'Lys-27'-linked ubiquitination of MAVS, leading to the recruitment of TBK1 and up-regulation of innate immunity. Mediates 'Lys-63'-linked polyubiquitination of G3BP1 in response to heat shock, leading to stress granule disassembly.
Synonyms: RNF81; RO52; SSA1; TRIM21/Ro52; Ro/SSA; SSA
Tractability: Small molecule: a structure with a bound ligand is known. PROTAC: UniProt records ubiquitination sites on it; ubiquitination databases record sites on it; its protein half-life has been measured.
Gene: Protein-coding gene on chromosome 11 (4,384,897 to 4,393,747, reverse strand). Ensembl gene ENSG00000132109.
Subcellular location: Cytoplasm; Cytoplasmic vesicle, autophagosome; Nucleus; Cytoplasm, P-body; Cytoplasm, Stress granule
Subcellular location (Human Protein Atlas): Nucleoplasm
Pathways (Reactome):
Immune System: Antigen processing: Ubiquitination & Proteasome degradation; Interferon gamma signaling; Regulation of innate immune responses to cytosolic DNA; STING mediated induction of host immune responses
Cellular responses to stimuli: KEAP1-NFE2L2 pathway
Gene Ontology:
Molecular function: identical protein binding; protein binding; transcription coactivator activity; ubiquitin protein ligase activity; ubiquitin-protein transferase activity; metal ion binding; zinc ion binding
Biological process: antiviral innate immune response; negative regulation of innate immune response; negative regulation of protein deubiquitination; positive regulation of autophagy; positive regulation of cell cycle; positive regulation of non-canonical NF-kappaB signal transduction; positive regulation of protein binding; proteasomal protein catabolic process; protein autoubiquitination; protein destabilization; protein K27-linked ubiquitination; protein K48-linked ubiquitination; protein K6-linked ubiquitination; protein K63-linked ubiquitination; protein monoubiquitination; protein polyubiquitination; protein ubiquitination; pyroptotic inflammatory response; response to type II interferon; stress granule disassembly; suppression of viral release by host; cellular response to chemical stress; innate immune response; regulation of gene expression; regulation of type I interferon production; and 1 more
Cellular component: cytoplasm; cytoplasmic stress granule; nucleus; SCF ubiquitin ligase complex; cytosol; ribonucleoprotein complex; autophagosome; P-body
Genetic constraint (gnomAD): Loss-of-function variants: 36 observed, 37.72 expected, observed/expected ratio (o/e) 0.95, 90% interval 0.73 to 1.26. The upper end of that interval is the gene's LOEUF score, 1.26, which puts it in group 5 of 6, group 1 being the genes least tolerant of losing a copy. Missense variants: 635 observed, 597.68 expected, observed/expected ratio (o/e) 1.06, 90% interval 1 to 1.13. Synonymous variants: 256 observed, 223.29 expected, observed/expected ratio (o/e) 1.15, 90% interval 1.03 to 1.27.
Homologues: Orthologues: chimpanzee TRIM21 (100% identical), macaque TRIM21 (96% identical), pig TRIM21 (76% identical), dog TRIM21 (75% identical), guinea pig TRIM21 (71% identical), rat Trim21 (69% identical), mouse Trim21 (68% identical). Paralogues in human: TRIM58 (41% identical), TRIM39 (38% identical), TRIM6 (38% identical), TRIM11 (37% identical), TRIM26 (36% identical), TRIM27 (35% identical), TRIM4 (35% identical), TRIM38 (35% identical), TRIM22 (33% identical), TRIM41 (33% identical), TRIML1 (33% identical), TRIM5 (33% identical), and 68 more.
Diseases named in the same sentence as TRIM21 in open-access papers:
TRIM21 is named in the same sentence as 302 diseases in open-access papers, as found by Europe PMC text mining. Sharing a sentence is not in itself a finding about the gene and the disease. The quoted sentences say what the papers report.
Sjögren’s syndrome (101 papers, 2006 to 2026). "In fact, for primary Sjögren’s syndrome (pSS), serological detection of anti-TRIM21 antibodies is a diagnostic criterion, with detection rates in patients ranging from 50-70% according to assay method." (PMID 34552597, 2021). "CENPB interacts also with TRIM21, an E3 ubiquitin ligase, involved in innate immunity, associated to cancer proliferation, as well as in systemic lupus erythematosus and in Sjögren’s syndrome." (PMID 34439361, 2021). "In a Norwegian population, the rs5030767 C/T, rs5030768 A/G, rs915956 C/T, and rs4144331 C/A SNPs were shown to be associated with anti-TRIM21-positive primary Sjogren's syndrome, among which rs915956 shows the strongest association." (PMID 34220328, 2021). "TRIM21 has been implicated in the chronic auto-immune condition systemic lupus erythematosus and is itself an auto-antigen in Sjögren’s syndrome." (PMID 31558002, 2016). "TRIM21 polymorphisms are also associated with autoimmune disease, and there may be a correlation between TRIM21 polymorphisms and disease susceptibility and increased production of TRIM21 antibodies in systemic lupus erythematosus and Sjogren's syndrome." (PMID 34220328, 2021). "In individuals with systemic lupus erythematosus (SLE) and Sjogren’s syndrome, increased TRIM21 expression downregulates BCL2, promotes extensive apoptosis, and compromises intracellular immunity." (PMID 38225560, 2024). "TRIM21 (class IV) is targeted by autoantibodies in Sjögren’s syndrome, an inflammatory autoimmune condition." (PMID 38115822, 2023). "Anti-Ro52 (TRIM21) antibody, one member of the ANA profile, is regarded to be associated with many autoimmune diseases, especially Sjogren’s syndrome, systemic lupus erythematosus, and systemic sclerosis." (PMID 35651612, 2022). "TRIM21 was originally identified as an autoantigen in autoimmune diseases, including rheumatoid arthritis, Systemic lupus erythematosus, and Sjogren’s syndrome." (PMID 34124071, 2021). "TRIM21, well known to play a role in innate immunity, systemic lupus erythematosus, and Sjögren’s syndrome, has been observed to participate in cancer proliferation." (PMID 35004288, 2021). "The most common TRIM21-associated autoimmune diseases are systemic lupus erythematosus (SLE) affecting the central nervous system, skin, kidneys and joints, and Sjögren’s syndrome (SS), which primarily affects the tear and salivary glands." (PMID 34552597, 2021). "TRIM21 was previously identified as an autoantigen for several autoimmune conditions, including Sjögren syndrome, rheumatoid synovitis, systemic sclerosis, and systemic lupus erythematosus." (PMID 31494268, 2019). "TRIM21 is also known as Ro52 and was first identified as a major autoantigen in autoimmune diseases such as Sjogren's syndrome and systemic lupus erythematosus (SLE)." (PMID 31555278, 2019). "TRIM21, also referred to as RNF81, Ro52, Ro/SSA, and SSA1, functions as a transcriptional regulator of type I interferon responses and is implicated in the pathogenesis of autoimmune disorders such as systemic lupus erythematosus and Sjögren syndrome." (PMID 40165656, 2025). "The STRING analysis here reveals that CENPB interacts with TRIM21, which is involved in both cancer proliferation and in innate immunity, possibly explaining its role in autoimmune diseases such as systemic lupus erythematosus and in Sjögren’s syndrome." (PMID 34439361, 2021). "Interestingly, both TRIM68 and TRIM21 are known autoantigens in SLE and primary Sjögrens syndrome (pSS), both autoimmune diseases associated with a high level of circulating type I IFN and an IFN-stimulated gene (ISG) signature." (PMID 24999993, 2014). "TRIM21, also known as Ro52, has the E3 ligase activity involved in the ubiquitination process and it was reported that autoantibodies against this protein were detected in patients with several autoimmune diseases, e.g., primary Sjögren’s syndrome." (PMID 24736434, 2014).
Sjögren’s syndrome (continued). "Protein tripartite motif-containing 21 (TRIM21/Ro52), an E3 ubiquitin ligase, is an essential regulator of innate immunity, and its dysregulation is closely associated with the development of autoimmune diseases, predominantly systemic lupus erythematosus (SLE) and primary Sjögren’s syndrome (pSS)." (PMID 37993883, 2023). "Both interactions play an essential role in pathological conditions related to Sjögren's syndrome and systemic lupus erythematosus (SLE), in which TRIM21 is recognized as an autoantigen and is likely to promote apoptosis." (PMID 38225560, 2024). "TRIM21/Ro52 and the antibodies that target it (anti-TRIM21/Ro52) are involved in many autoimmune diseases, especially rheumatic diseases, such as systemic lupus erythematosus (SLE) and primary Sjögren’s syndrome (pSS)." (PMID 37993883, 2023). "TRIM21 is one of the autoantigens that reacts with an anti-SS-A antibody (Ab) present in patients with systemic lupus erythematosus (SLE) and Sjögren's syndrome." (PMID 32117252, 2020). "Ro52/TRIM21 plays a key role in antibody-dependent pathogen neutralization and is a major autoantigen in systemic lupus erythematosus, Sjögren’s syndrome (SS), and other autoimmune diseases." (PMID 29463848, 2018). "TRIM21 was first described as a target for autoantibody production in SLE and Sjögren's syndrome (SS) and was amongst the first of the TRIM proteins shown to negatively regulate IFN production." (PMID 24999993, 2014). "TRIM21/Ro52/SS-A1, a 52-kDa protein, is an autoantigen recognized by antibodies in sera of patients with SLE and Sjögren's syndrome (SS), another systemic autoimmune disease, and anti-TRIM21 antibodies have been used as a diagnostic marker for decades." (PMID 22701487, 2012). "Tripartite motif containing 21 (TRIM21), a ~52-kDa protein also known as Ro52/SS-A, is one of major autoantigens recognized by anti-SS-A autoantibody present in sera of autoimmune diseases such as SLE and Sjögren's syndrome." (PMID 32117252, 2020). "In a later publication about the clinical practice of the Sjögren’s syndrome, it is stated that only anti-SS-A/Ro60 antibodies have to be considered, because isolated anti-Ro52/TRIM21 antibodies are not specific for the Sjögren’s syndrome." (PMID 32127033, 2020). "Other autoantibodies targeting Ro52 (also called TRIM21), Ro60, and ribonucleoprotein (Rnp-A) can also be found in SSc, but are not specific to SSc, and are seen in other systemic autoimmune diseases such as SLE, Sjögren’s syndrome, and myositis." (PMID 30913258, 2019). "Second, TRIM21, also known as Ro52/SSA, is a prominent antigen in Sjögren syndrome." (PMID 30481277, 2018). "Ro52 (also denoted TRIM21 and SSA1) is a member of the tripartite motif (TRIM) family of single-protein E3 ligases and is known to be a target for autoantibody production in systemic lupus erythematosus and Sjögren's syndrome." (PMID 20668674, 2010). "Interestingly, LAMP3 expression resulted in the accumulation and release of intracellular TRIM21 (one component of SSA), La (SSB), and α-fodrin protein, common autoantigens in Sjögren’s syndrome, via extracellular vesicles in an apoptosis-independent mechanism." (PMID 32939030, 2020). "Our findings of increased expression of TRIM21/Ro52 in lacrimal glands of MRL/lpr and NOD mice in the context of inflammation suggests this may contribute to the role of TRIM21/Ro52 as an autoantigen in Sjögren syndrome." (PMID 30481277, 2018). "Similarly, the original classification criteria for Sjögren’s syndrome include autoantibodies to SSA, but there is no differentiation between autoantibodies to SS-A/Ro60 and Ro52/TRIM21." (PMID 32127033, 2020).
systemic lupus erythematosus (98 papers, 2006 to 2025). An autoimmune multi-organ disease typically associated with vasculopathy and autoantibody production. "Previous studies have reported that TRIM21-deficient MRL/lpr mice presented with exacerbated lupus-like pathology, including increased levels of serum dsDNA antibody and urine protein, compared with wild-type (WT) MRL/lpr mice." (PMID 40610751, 2025). "Collectively, in two different lupus murine models, TRIM21 deficiency induced more severe lupus-like phenotype with increased IFNα production and STING pathway activation." (PMID 40610751, 2025). "To examine the effects of TRIM21 deficiency in a spontaneous lupus-prone mouse, we generated TRIM21-deficient B6.lpr (Trim21−/− B6.lpr) mice." (PMID 40610751, 2025). "In both induced and spontaneous murine models of lupus, TRIM21 deficiency exacerbated lupus-like pathology and heightened IFN production after STING activation." (PMID 40610751, 2025). "In MRL/lpr lupus susceptible mice, a dysfunction in TRIM21 was associated with the pathological progression of SLE, atypical B cell differentiation, elevated autoantibody levels, and proteinuria." (PMID 39165359, 2024). "In conclusion, we showed that TRIM21 deficiency promotes aberrant B-cell differentiation and Ab production, leading to exacerbation of the lupus-like symptoms in lupus-prone mice." (PMID 32117252, 2020). "Therefore, we evaluated the effect of TRIM21 deficiency on lupus manifestations in two independent lupus murine models." (PMID 40610751, 2025). "Similarly, TRIM21, an autoantigen associated with Systemic Lupus Erythematosus (SLE), negatively regulates type I IFN production driven by TLR3, TLR7, and TLR9." (PMID 40495154, 2025). "By inhibiting TRIM21 and related cytokines, anti-SSA/Ro52 antibodies may impair the innate immune response in lupus patients contributing to a higher risk for COVID-19." (PMID 35962159, 2022). "Interestingly, genome wide association studies have mapped lupus susceptibility genes to the genomic region that contains TRIM21, directly linking TRIM21 with the disease." (PMID 22479513, 2012). "Interestingly, in anti-Ro positive systemic lupus erythematosus (SLE) patients, increased TRIM21 mRNA associated to increased Type I IFN." (PMID 41050477, 2025). "The present study has revealed that TRIM21 can mitigate the STING-mediated production of type I IFN in murine lupus models." (PMID 40610751, 2025). "Collectively, TRIM21 overexpression by in vivo gene therapy attenuated lupus-like phenotypes and exerted anti-inflammatory effects on immune cell profiles in MRL/lpr mice." (PMID 40610751, 2025). "Nevertheless, TRIM21 is a known autoantibody target (leading to a low serum protein level) in diseases like systemic lupus erythematosus or other rheumatic autoimmune diseases, conditions that, in turn, are associated with PD." (PMID 38157091, 2023). "TRIM21 gene expression levels in PBMCs from unexposed lupus patients were lower in those with anti-SSA/Ro52 positive antibodies compared with negatives (0.106 vs 0.410, p = 0.004)." (PMID 35962159, 2022). "TRIM21 was also reported to contribute to abnormal cytokine production in Systemic lupus erythematosus (SLE)." (PMID 36139694, 2022). "TRIM21 was identified as a major autoantigen in autoimmune diseases including Sjögren's syndrome, systemic lupus erythematosus (SLE), and rheumatoid arthritis." (PMID 34712740, 2021). "Compared to lupus-prone (MRL/lpr) mice retaining functional TRIM21 activity, the spleens of TRIM21−/−MRL/lpr mice had significantly increased mature B cell numbers." (PMID 34552597, 2021). "This is the first report that shows the pathological role of TRIM21 dysfunction in the lupus mouse model." (PMID 32117252, 2020). "TRIM21 is an autoantigen which is found in the sera of patients with systemic lupus erythematosus (SLE), rheumatoid arthritis, and Sjögren’s syndrome." (PMID 32678213, 2020).